S100A16 (S100 calcium binding protein A16)
Diseases named in the same sentence as S100A16 in open-access papers (continued):
Sharing a sentence is not in itself a finding about the gene and the disease.
renal cell carcinoma (3 papers, 2022 to 2025). "S100A16 mRNA and protein levels correlate with overall worse survival and poor prognosis in renal cell carcinoma." (PMID 40846689, 2025). "Intervention of s100a16 can promote the progression and angiogenesis of renal cell carcinoma through the VEGF/VEGFR2 signal transduction pathway and lead to poor prognosis of renal cell carcinoma." (PMID 36176934, 2022). "Our research focused on the expression of S100A16 and its role in predicting the survival rate of renal cell carcinoma patients." (PMID 36176934, 2022). "Proliferation, migration, and angiogenesis were investigated in vitro, and the involvement of S100A16 in the undesirable biological events of renal cell carcinoma (RCC) was further explored." (PMID 36176934, 2022). "The calcium-binding protein S100A16 may contribute to the poor prognosis of RCC by boosting renal cell carcinoma development and angiogenesis through the VEGF/VEGFR2 signaling pathway." (PMID 36176934, 2022). "The objective of this study was to examine the relationship between S100A16 and renal cell cancer." (PMID 36176934, 2022). "To date, no research has reported the prognoses of individuals with S100A16 and renal cell cancer." (PMID 36176934, 2022).
renal fibrosis (3 papers, 2020 to 2024). A final common manifestation of a wide variety of chronic kidney diseases characterized by glomerulosclerosis and tubulointerstitial fibrosis. "Overexpression of S100A16 significantly accentuates the progression of renal fibrosis by upregulating the IRE1α/XBP1 pathways in HK-2 cells." (PMID 34645789, 2021). "Pretreatment with BAPTA-AM, a calcium chelator, blunted the upregulation of renal fibrosis genes and ER stress markers induced by S100A16 overexpression in HK-2 cells and suppressed the cytoplasmic colocalization of GRP78 and S100A16." (PMID 34645789, 2021). "Consistently, western blot of kidney tissues showed that overexpression of S100A16 in Tg mice promoted the expression of renal fibrosis-related proteins including fibronectin, α-SMA, and collagen I proteins, in contrast, S100A16 knockout significantly attenuated their expressions." (PMID 32094322, 2020). "In this study, we investigated the potential roles of S100A16 in renal fibrosis." (PMID 32094322, 2020). "Therefore, S100A16 is a critical regulator of renal tubulointerstitial fibroblast activation and is therefore a potential therapeutic target for the treatment of renal fibrosis." (PMID 32094322, 2020). "Furthermore, S100A16 knockout suppressed the TGF-β1-induced upregulation of Fibronectin, α-SMA expression, an indicator of renal fibrosis in NRK-52E cells." (PMID 38710691, 2024).
small cell lung carcinoma (3 papers, 2023 to 2025). Small cell lung cancer (SCLC) is a highly aggressive malignant neoplasm, accounting for 10-15% of lung cancer cases, characterized byrapid growth, and early metastasis. "Brain endothelial cell-derived EVs were responsible for upregulation of S100A16 in small cell lung cancer, promoting the survival of small cell lung cancer cells." (PMID 37509106, 2023). "At the molecular level, brain endothelial cell-derived exosomes were found to be responsible for the overexpression of S100A16 in small cell lung cancer cells." (PMID 37509106, 2023). "S100A16, in turn, promoted the survival of small cell lung cancer cells by preserving mitochondrial integrity and function." (PMID 37509106, 2023). "Functionally, S100A16 appears to be important in the metastasis of small-cell lung cancer cells to the brain." (PMID 37509106, 2023). "S100A16 also plays a key role in metastasis of small-cell lung cancer (SCLC) to the brain." (PMID 40846689, 2025).
acute kidney injury (2 papers, 2022 to 2024). Sudden and sustained deterioration of the kidney function characterized by decreased glomerular filtration rate, increased serum creatinine or oliguria. "In our previous study, we reported that S100A16 promotes acute kidney injury (AKI) by activating E3 ubiquitin ligase, the HMG-CoA reductase degradation protein 1 (HRD1), induced ubiquitination and degradation of GSK3β and CK1α, two β-catenin complex members." (PMID 38710691, 2024).
breast tumor (2 papers, 2024 to 2025). "There was a significant increase in the staining intensity of S100A16 in metastatic specimens, further solidifying the importance of S100A16 in metastatic breast tumor tissue." (PMID 40846689, 2025).
diabetic nephropathy (2 papers, 2020 to 2024). "One study mentioned the increased expression of S100A16 in the kidneys of diabetic mice, suggesting a potential link to diabetic nephropathy." (PMID 38710691, 2024). "One study demonstrated a significant increase in S100A16 expression in the kidneys of diabetic mice, suggesting a possible involvement in promoting kidney inflammation and fibrosis, key factors contributing to diabetic nephropathy." (PMID 38710691, 2024).
Esophageal carcinoma (2 papers, 2021 to 2023). A primary or metastatic malignant neoplasm involving the esophagus. "The expression of S100A16 was down-regulated in ACC (Adrenocortical carcinoma), ESCA (Esophageal carcinoma), KICH (Kidney Chromophobe), PRAD (Prostate adenocarcinoma), SKCM (Skin Cutaneous Melanoma), and TGCT (Testicular Germ Cell Tumors)." (PMID 33912559, 2021).
Insulin resistance (2 papers, 2019 to 2021). Increased resistance towards insulin, that is, diminished effectiveness of insulin in reducing blood glucose levels. "Relevant studies have shown that S100A16 can reduce the sensitivity of 3T3-L1 to insulin, overexpression of S100A16 can promote lipid synthesis of 3T3-L1 preadipocytes, inhibiting glucose uptake under insulin stimulation, and cause insulin resistance." (PMID 33912559, 2021). "Consistent with this, we showed that overexpression of S100A16 induced lipid accumulation in adipose and liver tissue, and triggered insulin resistance." (PMID 31399502, 2019).
kidney damage (2 papers, 2020 to 2024). "The S100A16 protein was weak in normal human kidneys biopsies; whereas the strong S100A16 signals was detected in all specimens from clinical nephropathy samples." (PMID 32094322, 2020). "In this study, S100A16 expression was examined by immunohistochemical staining of kidney biopsy specimens from patients with various nephropathies and kidney tissues from a unilateral ureteral obstruction (UUO) mouse model." (PMID 32094322, 2020). "In our previous studies, we reported that the expression of S100A16 is significantly increased in kidney biopsy specimens from patients with various clinical nephropathy and kidney disease mouse models, including IRI model and unilateral ureteral occlusion (UUO) model." (PMID 38710691, 2024). "Moreover, S100A16 is also highly expressed in kidney biopsy specimens from patients with various clinical nephropathy." (PMID 38710691, 2024). "We reported that S100A16 activated HRD1, an E3 ubiquitin ligase, that degraded GSK3β and CK1α, the major members of the β-catenin degradation complex, then allowed β-catenin to release and translocate to the nucleus, leading to severe kidney damage." (PMID 38710691, 2024).
leukemia (2 papers, 2020 to 2022). A malignant (clonal) hematologic disorder, involving hematopoietic stem cells and characterized by the presence of primitive or atypical myeloid or lymphoid cells in the bone marrow and the blood. "The exclusively up-regulated genes in BC cells included SOCS2 and S100A16, which are pivotal in promoting progression of leukemia as well as other types of cancer." (PMID 33226961, 2020).
metastasis (2 papers, 2015 to 2025). The spread or migration of cancer cells from one part of the body (where they first appeared) to another. "respectively), whereas higher S100A16 expression was also significantly associated with tumor size (P= 0.007) and lymph node metastasis (P < 0.001)." (PMID 25884418, 2015). "Samples were stratified based on lymph node metastasis status (positive or negative), and S100A16 expression levels were assessed using bulk RNA-seq data." (PMID 40846689, 2025).
osteosarcoma (2 papers, 2012 to 2025). A usually aggressive malignant bone-forming mesenchymal neoplasm, predominantly affecting adolescents and young adults. "In our study, we focused on the role and mechanism of S100A16 in osteosarcoma and found that S100A16 is highly expressed in osteosarcoma samples, with its expression levels closely associated with the proliferation, migration, and invasion capabilities of osteosarcoma cells." (PMID 40481236, 2025). "Firstly, by analyzing databases and assessing mRNA and protein level, we found that the expression of S100A16 was significantly promoted in osteosarcoma, as compared with normal tissue." (PMID 40481236, 2025). "S100A16 gene was reported to highly expressed in several tumor tissues while the relationship between S100A16 and osteosarcoma remains less well-understood." (PMID 40481236, 2025). "Cellular experiments showed that the S100A16 promoted osteosarcoma progression by activating the PI3K/AKT signaling pathway, and upregulated expression of ANXA2, a crucial protein in occurrence and development of tumors." (PMID 40481236, 2025). "This study aimed to investigate the expression characteristics of S100A16 in osteosarcoma and the mechanism by which it promotes osteosarcoma progression." (PMID 40481236, 2025). "Then transfection techniques were employed to upregulate and downregulate S100A16 in osteosarcoma cells, the results demonstrated that S100A16 can increase osteosarcoma cell viability, migration and invasion capacities, while decline osteosarcoma cell apoptosis." (PMID 40481236, 2025). "In contrast, reports regarding the impact of S100A16 on osteosarcoma remain scarce." (PMID 40481236, 2025). "Further research indicates that S100A16 activates the PI3K/AKT signaling pathway by regulating the expression of ANXA2, thereby promoting the development of osteosarcoma." (PMID 40481236, 2025).
renal carcinoma (2 papers, 2022 to 2025). A carcinoma arising from the epithelium of the renal parenchyma or the renal pelvis. "Silencing of S100A16 in renal cancer cell lines reduced their migratory potential, facilitated through VEGF and AKT signaling pathways." (PMID 40846689, 2025). "Western blot analysis results revealed that transfection of shRNA-S100A16 substantially inhibited the expression level of S100A16 protein in renal cancer 796-P cells compared with the control group (shRNA-control)." (PMID 36176934, 2022). "Fluorescence quantitative PCR results demonstrated that the transfection of shRNA-S100A16 substantially inhibited the expression level of S100A16.0 mRNA in renal cancer 796-P cells compared with the control group (shRNA-control)." (PMID 36176934, 2022). "Compared with the control group (shRNA-control), the transfection of the S100A16 knockdown vector (shRNA-S100A16) dramatically inhibited angiogenesis in the renal cancer cells." (PMID 36176934, 2022). "We first compared the expression levels of S100A16 in normal renal tubular epithelial cells (HK-2) and renal cancer cell lines (ACHN, 796-p, 786-O, and Caki02)." (PMID 36176934, 2022). "Similar to ordinary renal tubular epithelial cells (HK-2), S100A16 was strongly expressed in renal cancer cell lines, with the 796-P cell line exhibited the highest expression level." (PMID 36176934, 2022). "We performed an angiogenesis experiment to determine the effect of knocking down S100A16 expression on the angiogenesis of renal carcinoma cells." (PMID 36176934, 2022). "796-P cells were transfected with an S100A16 knockdown vector (shRNA-S100A16) and a control group (shRNA-control), and the unique regulatory role of S100A16 in renal cancer cells was characterized." (PMID 36176934, 2022). "The findings of the Transwell cell migration experiment demonstrated, compared with the control group (shRNA-control), the transfection of the S100A16.0 knockdown vector (shRNA-S100A16) substantially inhibited renal cancer cell movement." (PMID 36176934, 2022). "The findings suggested that the suppression of S100A16 inhibits the proliferation, clone formation, and migration of renal cancer cells." (PMID 36176934, 2022). "By using The Cancer Genome Atlas (TCGA) database, the differentially expressed gene S100A16 was identified, and its appearance and link to the prognosis of persons with renal cancer were confirmed." (PMID 36176934, 2022). "Additionally, the effects of S100A16 on the proliferation and migration of renal cancer cells were investigated using a CCK-8 detection assay." (PMID 36176934, 2022). "Fluorescence quantitative PCR was used in identifying renal cancer cell lines (ACHN, 796-p, 786-O, and Caki02) and standard renal hollow epithelial cells (HK-2), and the effects of S100A16 on the onset and progression of renal growth were investigated." (PMID 36176934, 2022). "The findings indicated that related control cluster (shRNA-control), the S100A16.0 knockdown vector (shRNA-S100A16), can be transfected, significantly inhibiting the capacity of kidney carcinoma cells to proliferate." (PMID 36176934, 2022). "Moreover, the angiogenesis studies demonstrated that the suppression of S100A16 may reduce the expression levels of VEGF, VEGFR2, and p-Akt in renal cancer cells, consequently diminishing their angiogenesis capacities." (PMID 36176934, 2022). "Compared with the control group (shRNA-control), the transfection of the S100A16.0 knockdown vector (shRNA-S100A16) dramatically suppressed the production of VEGF, VEGFR2, and phosphorylated AKT (p-Akt) in renal cancer cells but had no impact on the expression of total Akt." (PMID 36176934, 2022).
steatosis (2 papers, 2022 to 2023). Increased lipid within the cytoplasm of cells. "S100a16 knockdown alleviated ethanol-induced liver injury, steatosis and inflammation." (PMID 37928262, 2023). "Indeed, transgenic mice overexpressing constitutively S100A16 had a more severe steatosis than control mice when fed a high-fat-containing diet (HFD) inducing obesity, steatosis and IR." (PMID 36232334, 2022).
alcoholic fatty liver disease (1 paper, 2023). Lipid infiltration of the hepatic parenchymal cells that is due to alcohol abuse. "To elucidate the relationship between S100A16 and alcoholic fatty liver disease, we generated S100a16 knockout mice." (PMID 37928262, 2023).
asthma (1 paper, 2016). "In this study, we found that the expression of S100P and S100A16 genes were significantly increased in the asthma group at 4 h post-meal compared with baseline." (PMID 26751474, 2016). "qPCR confirmed that S100P, S100A16, MAL and MUC1 were significantly increased in the asthma group post-meal." (PMID 26751474, 2016). "Confirming the microarray analysis, we determined that S100P, S100A16, MAL and MUC1 were significantly increased in the asthma group at 4 h post-meal compared with baseline." (PMID 26751474, 2016).
autoimmune hepatitis (1 paper, 2020). Hepatitis caused by autoantibodies. "It is worth noting that FTCD is associated with autoimmune hepatitis, and S100A16 plays an important role in the development of various malignant tumors." (PMID 33224891, 2020).
fatty liver (1 paper, 2023). "Subsequently, we examined the underlying mechanism of S100A16 in regulating alcoholic fatty liver injury." (PMID 37928262, 2023). "Contrasting with the effects of S100a16 suppression, overexpression of S100a16 exacerbated the progression of alcohol-induced fatty liver development compared with WT mice." (PMID 37928262, 2023). "Collectively, these findings compellingly argued that overexpressing S100A16 intensified the manifestations of alcohol-induced hepatic steatosis and injury." (PMID 37928262, 2023). "Additionally, the knockdown of S100a16 has shown potential in mitigating fatty liver injury." (PMID 37928262, 2023). "In summation, S100a16 ablation augmented MANF expression, thereby curtailing ER stress, which in turn mitigates the progression of alcoholic fatty liver development." (PMID 37928262, 2023).
kidney cancer (1 paper, 2022). Primary or metastatic malignant neoplasm involving the kidney. "The findings of the clone creation experiment demonstrated that, compared with the control group (shRNA-control), the transfection of the S100A16.0 knockdown vector (shRNA-S100A16) greatly inhibited the capacity of kidney cancer cells to generate clones." (PMID 36176934, 2022).
liver fibrosis (1 paper, 2023). "Our data further indicated that silencing of S100a16 can protect mice from liver fibrosis when exposed to stimuli such as CCl4, bile duct ligation surgery, and methionine choline deficiency diet feeding." (PMID 37928262, 2023). "Our previous studies showed the association of S100A16 with adipogenesis 33, 34, NFALD 7 and liver fibrosis." (PMID 37928262, 2023).
metabolic syndrome (1 paper, 2014). A cluster of metabolic risk factors for CARDIOVASCULAR DISEASES and TYPE 2 DIABETES MELLITUS. "The aim of this study is to determine the effects of E2 on metabolic syndrome and the molecular mechanisms involving S100A16." (PMID 24501224, 2014).
metastatic tumor (1 paper, 2017). "TRFC was shown originally to be significantly induced in DU145 cells, CORO1C/coronin was found to be induced in androgen-insensitive PCa and S100A16 appears to be upregulated only in metastatic tumor cells." (PMID 28163933, 2017).
type 2 diabetes mellitus (1 paper, 2022). A type of diabetes mellitus that is characterized by insulin resistance or desensitization and increased blood glucose levels. "S100A16 has been shown to be associated with obese, type 2 diabetes mellitus and inflammation via calcium-dependent mechanism." (PMID 35958614, 2022).